TNF (tumor necrosis factor)
Diseases named in the same sentence as TNF in open-access papers (continued):
Sharing a sentence is not in itself a finding about the gene and the disease.
glioblastoma (180 papers, 1994 to 2026). The most malignant astrocytic tumor (WHO grade IV). "This pathway was also implicated in the sensitization of glioblastoma cells to TNFα through the NFκB inhibitor, Ebselen, and NFκB-dependent TMZ-sensitization through IAP inhibitor BV6." (PMID 38212807, 2024). "In brief, we demonstrated that exposure of 1 to glioblastoma cells caused time and concentration-dependent upregulation of endogenous TNFα and TNFR1 receptor." (PMID 38212807, 2024). "We used human primary M2 microglia, SK-N-SH neuroblastoma, and U-87 MG glioblastoma cells to validate the association between TNF-α and NAC-induced cell mortality." (PMID 36835209, 2023). "According to our data, reduced cytotoxic activity of glioblastoma patient-derived DCs was associated with low TNFα mRNA levels." (PMID 32326230, 2020). "Glioblastoma patient IFN-DCs showed lower cytotoxicity against autologous glioblastoma cells sensitive to TNFα/TNFR1-mediated lysis, which was associated with low TNFα mRNA expression and high TACE/ADAM-17 enzyme activity." (PMID 32326230, 2020). "We therefore utilized the TCGA glioblastoma database to evaluate the presence of common glioblastoma mutations and expression of TNFα signaling mediators in patients with different levels of A20 expression." (PMID 20186265, 2010). "The mechanism by which tumour necrosis factor (TNF)-alpha increases the susceptibility of U87-MG human glioblastoma cells to lysis by natural killer (NK) cells was studied." (PMID 7908214, 1994). "Moreover, GAMs are associated with the radio-obstruction of glioblastoma by discharging TNF α, which increments the atomic element κB (NF-κB) that is connected with substandard endurance." (PMID 37237548, 2023). "Thus, inhibition of cytotoxic ligands/mediators revealed that two main pathways underlie cytotoxic activity of donor IFN-DCs against most glioblastoma cells, i.e., granule-dependent and TNFα/TNF-R1-dependent pathways." (PMID 32326230, 2020). "Interestingly, the anti-inflammatory cytokine IL-10 is increased in the glioblastoma patients which has already been reported in association with immunosuppression in glioblastoma, whereas TNFα serum levels were unaltered." (PMID 31155685, 2019). "In a murine glioblastoma setting, administration of the bevacizumab analog B20.4.1.1 was associated with heightened TNF-α release by GAMs and increased endothelial activation—findings that may underlie the observed inefficacy of anti-angiogenic strategies in glioblastoma treatment." (PMID 41479886, 2025). "One study found that knocking down APOE in glioblastoma cells altered cytokine secretion (increased IL-6/IL-12/TNF-α and decreased CCL5/TGF-β) and reduced the proportion of M2 macrophages in a co-culture system." (PMID 40745073, 2026). "This case highlights genomic features of an IDH-wild-type glioblastoma arising after prolonged TNF-α inhibitor exposure." (PMID 42130630, 2026). "The pro-inflammatory cues of several reputed pharmacological agents including ConA, PMA, TNFα, and TGFβ were therefore assessed in U87 glioblastoma cells as well as in MDA-MB-231 TNBC-derived cells." (PMID 40248812, 2025). "The activation of the GPR68-ATF4 signaling pathway can promote the production of the pro-inflammatory factors IL-6 and TNF-α and helps glioblastoma cells to evade immune surveillance, thus enhancing the growth and survival of glioblastoma cells." (PMID 41190345, 2025). "In human glioblastoma cells, oleuropein and hydroxytyrosol protected against tumor necrosis factor‐induced cyclooxygenase expression." (PMID 40979569, 2025). "RES, by down-regulating the PI3K/AKT/NF-κB pathway, inhibits the invasion of glioblastoma-initiating cells in glioblastoma, and in human glioma cells U373M, it regulates NF-κB-dependent TNF-α expression by reducing cell invasion." (PMID 40077707, 2025).
glioblastoma (continued). "Through the enrichment analysis, it can be discovered that the synergistic effect of Mel and TMZ on glioblastoma is primarily related to apoptosis and TNF signalling pathways." (PMID 40804775, 2025). "Glioblastoma-derived IL-8 and CCL2 chemokines can activate glioma-associated GAMs, which, in turn, secrete TNF-α, thereby triggering gene expression programs in ECs characteristic of an activated state." (PMID 41479886, 2025). "We further extended our pharmacological screen to PMA and TNFα, two reputed inducers of inflammation in U87 glioblastoma cells." (PMID 40248812, 2025). "Markers of innate immunity including CD68, S100A9, HLADR, NLPR3, interleukin (IL) 1β, IL-6, TNFα and NF-κB were significantly increased in human derived glioblastoma samples compared to healthy control brain." (PMID 41034696, 2025). "MAP3K8 acts as a convergence node for TNF-α and Toll-like receptor (TLR) signaling, triggering ERK and JNK cascades, both of which are implicated in glioblastoma stemness, invasion, and resistance to therapy." (PMID 40565357, 2025). "The concentration-dependent elevation of TNF-α suggests that these NPs can modulate inflammatory pathways within glioblastoma cells, potentially impacting tumor growth and immune surveillance." (PMID 39398744, 2024). "Contrary to glioblastoma cells, TNF-α stimulated HUVECs treated with just NeutrAvidinTM and the biotinylated liposomes show significant aspecific binding." (PMID 38399288, 2024). "TGF beta signaling also activates TNF signaling via NF-kB in glioblastoma, which in turn induces mesenchymal transition." (PMID 38981682, 2024). "Th-ZnNPs were found to increase TNF-α expression in glioblastoma cells in a concentration-dependent manner." (PMID 39398744, 2024). "As a proof-of-concept, we demonstrate that the inhibition of NFκB by palbociclib-MHI 148 conjugate sensitizes glioblastoma cells to TNFα treatment." (PMID 38212807, 2024). "Despite TNFα’s ability to induce apoptosis, glioblastoma is reportedly resistant to TNFα-mediated apoptosis." (PMID 38212807, 2024). "H2A.J expression in mesenchymal type of glioblastoma is associated with Proneural-Mesenchymal Transition (PMT) and activation of Tumor Necrosis Factor—Alpha (TNF-α)/Nuclear Factor Kappa-light-chain-enhancer of activated B cells (NF-κB) pathways." (PMID 38542118, 2024). "In therapeutic models, EGFR inhibition promotes TNF-α activation in glioblastoma and increases TNF-α-induced lung epithelial cell apoptosis and pulmonary injury." (PMID 38789573, 2024). "Another study in 15 recurrent glioblastoma patients showed that TNFα, IFNγ and IL-6 were increased in cerebrospinal fluid 72 h after treatment with the adenovirus Delta24-RGD." (PMID 39196415, 2024). "Specifically, the transcription and translation of CH25H have been found to increase in response to TNFα and IL1β in glioblastoma cell lines." (PMID 37208656, 2023). "In vitro glioblastoma’s ability to invade and infiltrate, NF-κB p65 (RelA) and TNFα play crucial roles, according to a wealth of evidence." (PMID 37892820, 2023). "In vitro expression study of NF-κB p65 (RelA) and TNFα in the SF-767 glioblastoma cell line after treatment with temozolomide and celecoxib." (PMID 37892820, 2023). "To evaluate the potential role of NF-κB p65 (RelA) and TNFα in glioblastoma, we quantified the expression of NF-κB p65 (RelA) and TNFα in 33 GBM samples." (PMID 37892820, 2023). "Compared to the stress group, celecoxib significantly reduced the expression of NF-κB p65 (RelA) and TNFα in the glioblastoma SF-767 cell line in a dose-dependent manner." (PMID 37892820, 2023). "This study investigated the molecular mechanism of TNF related-lncRNAs and their immune characteristics in glioblastoma multiforme (GBM) patients." (PMID 37153654, 2023).
glioblastoma (continued). "Regarding its function, TCC88 showed in vitro cytotoxicity against an autologous glioblastoma cell line and a multifunctional pro-inflammatory phenotype with strong secretion of TNF, IFNγ, granzyme B, GM-CSF and others." (PMID 37198490, 2023). "Although TNFα expression was increased in a number of malignancies, it was shown that glioblastoma had the highest amount of enhanced TNFα expression." (PMID 37892820, 2023). "mRNA and protein expression of NF-κB p65 (RelA) and TNFα were significantly increased in glioblastoma biopsy samples." (PMID 37892820, 2023). "Compared to the stress group, the TMZ did not significantly reduce the expression of NF-κB p65 (RelA) and TNFα in the glioblastoma SF-767 cell line in a dose-dependent manner." (PMID 37892820, 2023). "NF-κB activation mediates apoptotic signals during chemotherapy in sarcoma cells, TNF-α -treated adenocarcinoma cells, and glioblastoma cells." (PMID 36770846, 2023). "Results: demonstrated the upregulation of NF-κB p65 (RelA) and TNFα and celecoxib reduced the viability of the human glioblastoma cell line SF-767, cell proliferation, and NF-κB p65 (RelA) and TNFα expression in a dose-dependent manner." (PMID 37892820, 2023). "Tyrosol, hydroxytyrosol, and oleuropein, which are phenolic substances found in olive oil, can reduce the impact of the chronic inflammatory milieu on glioblastoma by regulating TNF-α, COX-2, JNK, ERK, and NF-kB." (PMID 35893883, 2022). "IP‐10 has been found to synergize with the fourth potential biomarker, TNF‐α, in a murine model of glioblastoma." (PMID 35790025, 2022). "Global analysis of RNA showed that MCP1 mRNA was strongly upregulated in glioblastoma cells when treated with tumor necrosis factor α (TNFα) in a sustained manner and at the highest level of all analyzed genes." (PMID 36077021, 2022). "Overall, these data indicate that TNFα treatment of glioblastoma cells nicely recapitulates MT process." (PMID 35851726, 2022). "Some research show that EZH2 inhibition leads to significant reduction of M2 markers (CD206) and elevation of M1 markers (TNFα and iNOS) in TAMs co-cultured with murine glioblastoma cells." (PMID 36038549, 2022). "Glioblastoma multiforme (GBM) is an aggressive brain tumor which tends to arise sporadically but may be associated with anti-TNF therapies." (PMID 35719803, 2022). "Interferon-γ (IFNγ), tumor necrosis factor-α (TNFα), granzyme B, and IL-4 levels were significantly increased in iNKT cells stimulated with the α-GalCer-pulsed glioblastoma cell lines in a CD1d-dependent manner." (PMID 33128583, 2021). "The synergistic effect of cytokines TNF-α and IL-6 ascertained the belligerent nature of glioblastoma through activation of the NF-κB and STAT3 pathways." (PMID 34439380, 2021). "The data obtained characterized a direct cytotoxic effect of IFN-DCs on glioblastoma cells and demonstrated a selective (TNFα/TNF-R1-mediated) defect in this function in DCs derived from glioblastoma patients." (PMID 32326230, 2020). "Intracranial glioblastoma cells are also sensitive to the effects of IAP antagonists (either LCL161 or birinapant) in combination with exogenous TNF or TRAIL." (PMID 31947615, 2020). "We previously reported that monocyte-derived IFNα-induced DCs (IFN-DCs) of glioblastoma multiforme patients express low levels of membrane TNFα molecule (mTNFα) and have impaired TNFα/TNF-R1-mediated cytotoxicity against immortalized tumor cell line HEp-2." (PMID 32326230, 2020). "The data obtained revealed a defect in TNFα/TNF-R1-dependent DC cytotoxicity against autologous tumor cells in glioblastoma patients." (PMID 32326230, 2020). "IFN-DCs from glioblastoma patients were characterized by more than a twofold decrease in TNFα mRNA levels in comparison with donor IFN-DCs (Me 2−ΔΔCt = 0.35; p = 0.05)." (PMID 32326230, 2020).
glioblastoma (continued). "An important observation was made in the present study in that among the receptor-mediated pathways studied it was TNFα/TNF-R1-dependent mechanism that was involved in the vast majority of cases in lysis of glioblastoma cells by dendritic cells." (PMID 32326230, 2020). "Only when glioblastoma cells were resistant to TNFα-mediated lysis (GB #10), cytotoxic activities were the same for healthy donor-derived and patient-derived DCs." (PMID 32326230, 2020). "Defective cytotoxic activity of IFN-DCs derived from glioblastoma patients against autologous tumor cells was observed only in the cell lines sensitive to TNFα/TNF-R1-mediated lysis." (PMID 32326230, 2020). "As expected, the pro-inflammatory cytokine TNF-α was highly expressed in glioblastoma cells, and its expression was significantly reduced following BCP treatment, probably as a consequence of NF-κB reduction and PPAR-γ activation." (PMID 32340197, 2020). "Because TNIP1 is involved in NF‐κB signalling in multiple immune diseases, we investigated several TNF‐α/NF‐κB signalling members in glioblastomas." (PMID 31691497, 2020). "Other studies identified JNK1/2 as the main regulator of ITCH-induced c-FLIP degradation after TNFα stimulation or AKT inhibition in glioblastoma." (PMID 31443721, 2019). "One study in glioblastoma showed that TNFα stimulation decreased p-ERK expression, led to reduction of YAP1 expression." (PMID 31848326, 2019). "In glioblastoma cells resistant to TNFα, CK2 inhibitors have been found to restore sensitivity by abrogating NF-κB activation." (PMID 31277672, 2019). "Ketamine reduces NFkB activation in A172 human glioblastoma cells exposed to LPS and reduces TNFα and IL6 production by LPS-stimulated RAW 267.4 (transformed mouse macrophage) cells." (PMID 30666211, 2018). "Despite this differential requirement of TRAIL signaling in glioblastoma cells, both TNFα and TRAIL expression was upregulated by IFNα/Smac mimetic cotreatment." (PMID 29371590, 2018). "In this study, after LPS incubation with U87 glioblastoma cell, the pro-inflammatory cytokine TNFα, IL1β, and IL6 levels were elevated; the response was reversed by co-incubation of polysaccharide fractions in LPS." (PMID 29530027, 2018). "In vitro study, aluminum initiated inflammatory in a human glioblastoma cell line, which can be chalked up to the activation of the immune-responsive transcription factor NF-κB and elevation of TNF-α in a time-dependent manner." (PMID 29190893, 2017). "It demonstrated a possible role of CBD-induced signaling cascades for regulation of TNF gene expression in glioblastoma cells." (PMID 29088769, 2017). "Activation of NF-κB by TNFα decreases calcium induced mPTP opening, elevates mitochondrial potential and increases reactive oxygen species (ROS) production in both T98G human glioblastoma cells and rat cortical neurons." (PMID 28317877, 2017). "We confirmed that the synergistic effects between the SMC, LCL161, and TNF-α is a general phenomena within this drug class, as we observed death of glioblastoma cells with the combination of TNF-α and different SMCs." (PMID 28198370, 2017). "To assess a role of endogenously produced TNFα and TRAIL after CBD treatment of glioblastoma cells, we added inhibitory antibody against TNFα (5 μg/ml) or against TRAIL into the culture media before CBD treatment." (PMID 29088769, 2017).
glioblastoma (continued). "Secretion of TNFα was also substantially increased in both glioblastoma lines after CBD treatment with a relatively small positive effect of irradiation in combination with CBD for U118MG cells." (PMID 29088769, 2017). "As we previously noted that the type I IFN response also leads to the production of TNF-α16, we assessed the ability of T-cells to produce TNF-α following SMC treatment in the presence of glioblastoma cells." (PMID 28198370, 2017). "It is speculated that constitutive activation of NF-κB in glioblastoma multiforme (GBM) may be associated with tumor resistance to TNF-α immunotherapy." (PMID 17565690, 2007). "The small molecules from T. versicolor (SMCV) not only have indirect anti-cancer effects by inhibiting TNF-α-induced MMP-3 production in glioblastoma T98G cells but also directly reduce the invasive ability of malignant cells such as T98G, A549, and MDA-MB-231 cells." (PMID 40507156, 2025). "Ketamine has also demonstrated anti-inflammatory potential in vitro, where it was observed to inhibit the production and release of pro-inflammatory cytokines, such as IL-6, IL-1β and TNF-α, in murine macrophages, primary rat microglial cells and human-derived glioblastoma cells." (PMID 40498007, 2025). "More recently, it has been reported that infection of human glioblastoma cell line with Ad/mda7 enhanced both the activation of apoptosis through the tumor necrosis factor-α (TNF-α) family of death receptors and autophagy, which was triggered by the upregulation of LC3-II." (PMID 40806452, 2025). "In addition, the study reported that APOE knockdown in glioblastoma cells attenuated tumor migration/invasion while reprogramming cytokine secretion—elevating antitumor cytokines (IL-6/IL-12/TNF-α) and suppressing immunosuppressive CCL5/TGF-β." (PMID 41390817, 2025). "Understanding the mechanisms that determine the fate of TNFα signalling may provide the opportunity to identify novel therapeutic targets to sensitize glioblastoma tumours to TNFα treatment." (PMID 38212807, 2024). "Interestingly, our investigation showed manifested that conjugation of palbociclib to MHI-148 resulted in TNFR1 upregulation and the release of endogenous TNFα from glioblastoma cells." (PMID 38212807, 2024). "Interestingly, treatment of glioblastoma cells with 1 resulted in significant TNFα secretion (p < 0.0001, one-way ANOVA), relative to both vehicle and palbociclib treatment." (PMID 38212807, 2024). "The content of glioblastoma exosomes and the effect of TNF-α." (PMID 39088270, 2024). "Moreover, inhibition of NFκB translocation has been shown to sensitize glioblastoma cells to TNFα treatment; hence, IKK inhibitor, TPCA-1 (10 μM) was used as a positive control." (PMID 38212807, 2024). "Since CDK4/6 activates NFκB signalling, we have examined whether blockade of CDK4/6 with palbociclib-MHI 148 conjugate, 1, could activate the endogenous TNFα mediated apoptosis pathway in glioblastoma." (PMID 38212807, 2024). "Inhibition of TNFα-induced IκBα phosphorylation by BAY 11–7082 was reported in glioblastoma cells." (PMID 37853467, 2023). "Moreover, in the serum of patients with glioblastoma (the most typical parenchymal brain tumor), it has been reported that there is a significant overexpression of IL-6, IL-1β, TNF-α, IL-10, VEGF, FGF-2, IL-8, IL-2, and GM-CSF." (PMID 37368708, 2023). "Studies have found that cordycepin combined with doxorubicin may have activity against glioblastoma through proteoglycans in cancer, the TNF signaling pathway, microRNA in cancer, pathways in cancer, and other pathways." (PMID 35186504, 2022). "For example, a recent study performed in a murine model of human glioblastoma have shown that an RGD4C-directed hybrid virus of adeno-associated virus and phage (AAVP) can deliver the TNF gene to the tumors, and induce damage of tumor-associated neovessels and cell death." (PMID 35890309, 2022). "CLIPR-59 plays a role in glioblastoma resistance to TNFα-mediated apoptosis." (PMID 35805075, 2022).